NRTN (neurturin)
Description:
Growth factor that supports the survival of sympathetic neurons in culture. May regulate the development and maintenance of the CNS. Involved in the development of the neural crest. Might control the size of non-neuronal cell population such as haemopoietic cells. Acts by binding to its coreceptor, GFRA2, leading to autophosphorylation and activation of the RET receptor. Heparan sulfate-binding is required for signaling.
Synonyms: NTN
Tractability: Antibody: its Gene Ontology location is reachable by antibodies, with high confidence; UniProt places it where antibodies can reach, with medium confidence; UniProt predicts a signal peptide or a membrane-spanning region.
Gene: Protein-coding gene on chromosome 19 (5,805,056 to 5,828,324, forward strand). Ensembl gene ENSG00000171119.
Subcellular location: Secreted
Subcellular location (Human Protein Atlas): Golgi apparatus; Predicted to be secreted
Pathways (Reactome):
Developmental Biology: NCAM1 interactions; RET signaling
Signal Transduction: RAF/MAP kinase cascade
Gene Ontology:
Molecular function: growth factor activity; heparan sulfate binding; signaling receptor binding; glial cell-derived neurotrophic factor receptor binding; receptor tyrosine kinase binding
Biological process: glial cell-derived neurotrophic factor receptor signaling pathway; neural crest cell migration; neuron projection development; cell surface receptor protein tyrosine kinase signaling pathway; MAPK cascade; nervous system development; cell surface receptor signaling pathway via STAT
Cellular component: extracellular region
Genetic constraint (gnomAD): Loss-of-function variants: 2 observed, 5.47 expected, observed/expected ratio (o/e) 0.37, 90% interval 0.15 to 1.14. That is too few expected variants to judge how well the gene tolerates losing a copy. Missense variants: 307 observed, 210.46 expected, observed/expected ratio (o/e) 1.46, 90% interval 1.33 to 1.6. Synonymous variants: 156 observed, 99.12 expected, observed/expected ratio (o/e) 1.57, 90% interval 1.38 to 1.8.
Homologues: Orthologues: chimpanzee NRTN (100% identical), macaque NRTN (98% identical), pig NRTN (94% identical), dog NRTN (93% identical), guinea pig NRTN (90% identical), mouse Nrtn (86% identical), rat Nrtn (56% identical), tropical clawed frog nrtn (45% identical), zebrafish nrtn (32% identical). Paralogues in human: ARTN (34% identical), PSPN (28% identical), GDNF (27% identical).
Diseases named in the same sentence as NRTN in open-access papers:
NRTN is named in the same sentence as 42 diseases in open-access papers, as found by Europe PMC text mining. Sharing a sentence is not in itself a finding about the gene and the disease. The quoted sentences say what the papers report.
Parkinson disease (16 papers, 2009 to 2025). A progressive degenerative disorder of the central nervous system characterized by loss of dopamine producing neurons in the substantia nigra and the presence of Lewy bodies in the substantia nigra and locus coeruleus. "AAV2 was first used clinically in Canavan disease to deliver Aspartoacylase gene (ASPA), and later in Parkinson's disease trials to deliver neurturin." (PMID 41179895, 2025). "GDNF and the related family member Neurturin for the treatment of Parkinson's disease, Neurturin, as a potential key growth hormone in pancreas development, in diabetes, as well as GDF15 for obesity are particularly notable examples." (PMID 34495310, 2021). "When all these GDNF clinical trials were going on, other members of the GDNF neurotrophic factor family were being studied in Parkinson’s models especially Neurturin in the context of gene therapy." (PMID 33716718, 2021). "Two members of the GFL, GDNF and neurturin, have been evaluated in clinical trials for the treatment of Parkinson’s disease (PD)." (PMID 32046031, 2020). "We performed post-mortem studies on two patients with advanced Parkinson’s disease 8 and10 years following AAV2-neurturin (CERE120) gene therapy, the longest post-mortem trophic factor gene therapy cases reported to date." (PMID 32203581, 2020). "Another AAV-based neurotrophic factor therapy for human Parkinson’s disease patients has been neurturin (NRTN), a protein in the same family as GDNF." (PMID 28208742, 2017). "Parvalbumin interneurons in the dorsal striatum lose primary cilia in mice and humans harboring Parkinson’s disease–associated, activating mutations in LRRK2 kinase, resulting in loss of hedgehog signaling and decreased production of neuroprotective Neurturin to support dopamine neurons." (PMID 39537338, 2025). "Due to these properties, neurturin (NRTN) and Glial cell-derived neurotrophic factor (GDNF), which belong to the GDNF family ligands (GFLs), have been assessed in clinical trials as a treatment for neurodegenerative diseases like Parkinson’s disease." (PMID 32252363, 2020). "Indeed, TH-staining constituted a relatively large proportion of the NRTN-immunohistochemical footprint, whereas there was a comprehensive loss of TH-positive fibres in areas without detectable NRTN staining similar to Parkinson’s disease controls, as we have previously reported." (PMID 32203581, 2020). "This contrasts with the prior clinically negative viral vector neurturin studies in Parkinson’s disease, where no PET signal benefit was observed." (PMID 30808022, 2019).
glioma (2 papers, 2020 to 2022). A benign or malignant brain and spinal cord tumor that arises from glial cells (astrocytes, oligodendrocytes, ependymal cells). "RGMB, EDN1, SEMA3C and NRTN have been indicated to regulate olfactory neurogenesis, mesenchymal stem cells regeneration, tumorigenicity of glioma stem cells and neurite outgrowth, respectively." (PMID 35511361, 2022). "GDNF is a neurotrophic factor purified for the first time from a rat glioma cell line (B49) and belongs together with neurturin (NRTN), artemin (ARTN), and persephin (PSPN) to the family of GDNF ligands (GFL) belonging in turn to the superfamily of transforming growth factor β (TGF-β)." (PMID 33293946, 2020).
Hirschsprung disease (2 papers, 2019 to 2020). Hirschsprung disease (HSCR) is a congenital intestinal motility disorder that is characterized by signs of intestinal obstruction due to the presence of an aganglionic segment of variable extent in the terminal part of the colon. "NRTN variants are associated with Hirschsprung disease indicating that NRTN plays an important role in development of the peripheral nervous system." (PMID 32203581, 2020). "NRTN mutations have been associated with Hirschsprung’s disease, implicating that the NRTN-induced signaling of RET plays a role in the growth or guidance of enteric ganglia." (PMID 31535977, 2019).
breast tumors (1 paper, 2018). "However, only low levels of NRTN, ARTN, or their co-receptors were detected in primary breast tumors." (PMID 29608602, 2018).
colon tumors (1 paper, 2018). "Interestingly, ARTN, NRTN, GFRα1, and GFRα3 are found in colon tumors, potentially arising from gut nerves or associated with chronic inflammation of the intestine, which increases cancer risk, suggesting a subset of RET-expressing colon tumors may be responsive to GFL stimulation." (PMID 30666215, 2018).
diabetic retinopathy (1 paper, 2025). "Glial cell line-derived neurotrophic factor (GDNF) and neurturin facilitate glutamate uptake by retinal cells, which may help mitigate apoptosis and reflect a compensatory mechanism in response to neuroinflammation and neuronal damage typically seen in diabetic retinopathy." (PMID 41153721, 2025).
glaucoma (1 paper, 2024). Increased pressure in the eyeball due to obstruction of the outflow of aqueous humor. "Neurotrophic factors such as nerve growth factor (NGF), BDNF, CNTF, FGF-2, glial cell-line-derived neurotrophic factor (GDNF), neurturin (NRTN), and neuritin are particularly relevant to glaucoma." (PMID 39458902, 2024).
hepatocellular carcinoma (1 paper, 2024). A malignant tumor that arises from hepatocytes. "Moreover, MIA3 binds neurturin (NRTN), activating hepatocellular carcinoma cell proliferation and EMT, likely through the activation of the PI3K/AKT/mTOR pathway." (PMID 38928229, 2024).
Huntington disease (1 paper, 2018). Huntington disease (HD) is a rare neurodegenerative disorder of the central nervous system characterized by unwanted choreatic movements, behavioral and psychiatric disturbances and dementia. "Neurotrophic factors such as glial cell line-derived neurotrophic factor (GDNF), brain-derived neurotrophic factor (BDNF), and neurturin, for example, all appear to protect against the striatonigral degeneration in Huntington’s disease." (PMID 30524706, 2018).
impotence (1 paper, 2007). Inability to develop or maintain an erection of the penis. "In this study, the in vivo neuromodulatory effects of neurturin upon the recovery of erectile function following bilateral cavernous nerve crush injury are demonstrated using a rat model of neurogenic impotence." (PMID 17341313, 2007). "Treatment with neurturin at the site of cavernous nerve crush injury facilitates recovery of erectile function in a bilateral cavernous nerve crush injury model of erectile dysfunction in the rat." (PMID 17341313, 2007).
influenza (1 paper, 2020). An acute viral infection of the respiratory tract, occurring in isolated cases, in epidemics, or in pandemics; it is caused by serologically different strains of viruses (influenzaviruses) designated A, B, and C, has a 3-day incubation period, and usually lasts for 3 to 10 days. "Furthermore, increased NRTN was detected in the BAL fluid of influenza infected mice at time points associated with peak inflammation." (PMID 33020210, 2020).
malaria (1 paper, 2025). Malaria is a serious and sometimes fatal disease caused by a parasite that commonly infects a certain type of mosquito which feeds on humans. "Using proximity extension assay (PEA), we identified elevated IgG Fc receptor IIb (FCGR2B) and heme oxygenase-1 (HO-1) in malaria-positive pregnancies, while neurturin (NRTN) and IL-20 were downregulated." (PMID 40697816, 2025). "We observed that FCGR2B, HO-1, NRTN and IL-20 were differentially expressed in plasma from malaria-infected pregnant women vs. from non-malaria-infected controls." (PMID 40697816, 2025).
pancreatic cancer (1 paper, 2020). "In vitro matrigel-based invasion assay showed that NRTN enhances the invasiveness of pancreatic cancer cells and that it induces neuritogenesis of ex vivo dorsal root ganglions." (PMID 33142779, 2020). "For instance, GDNF and other members of the GDNF family (artemin, NRTN and persephin) were shown to play important cancer promoting roles in pancreatic cancer." (PMID 33142779, 2020).
psoriasis (1 paper, 2023). An autoimmune condition characterized by red, well-delineated plaques with silvery scales that are usually on the extensor surfaces and scalp. "Similarly, the role of neurturin in itching and intraepidermal fibre density in a mice model of psoriasis was demonstrated." (PMID 37663384, 2023).
rheumatoid arthritis (1 paper, 2026). A chronic, systemic autoimmune disorder characterized by inflammation in the synovial membranes and articular surfaces. "Rheumatoid arthritis: Six inflammatory factors, including Neurturin, Interleukin-6, Programmed cell death 1 ligand 1, CUB domain-containing protein 1, C-C motif chemokine 4, and CD40L receptor, are significantly associated with RA." (PMID 41399369, 2026).
spinal stenosis (1 paper, 2025). Narrowing of the spinal canal. "Neurturin (NRTN), a member of the glial cell line-derived neurotrophic factor family, has emerged as a potential mediator of neural plasticity and nociception, but its role in spinal stenosis is largely unexplored." (PMID 40426929, 2025).
viral infection (1 paper, 2020). "We determined that viral infection, or mimics thereof, specifically enhanced the production of the GFRα2 ligand, NRTN, from lung epithelium, whereas type I IFNs induced expression of the signalling receptor RET in lung macrophages." (PMID 33020210, 2020).
tumour (7 papers, 2016 to 2025). "In previous studies, CCL-28, FGF-19 and IL-2 were mostly investigated in immune disorders and tumor treatment 51-54, and neurturin was mainly discussed in muscular, neurodegenerative and psychiatric disorders 55,56." (PMID 40225870, 2025). "RET ligand, neurturin (encoded by the NRTN gene), is expressed by adrenocortical-like stromal cells in NB tumours, and its high expression correlates with a poor prognosis." (PMID 41511287, 2025). "The ELISA results demonstrated that circulating levels of interleukin‐4, interleukin‐6, and tumour suppressor‐M were significantly higher in AAA‐Exo samples, while MCP‐1 and Neurturin levels were significantly lower compared to healthy controls (p < 0.05)." (PMID 40770945, 2025). "Our analysis of MLS cell lines showed that they contained mRNAs for glia derived neurotrophic factor (GDNF), neurturin (NRTN) and persephin (PSPN) but RNA extracted from tumor tissues contained only the PSPN transcript." (PMID 26595521, 2016).
cancer (4 papers, 2020 to 2025). A tumor composed of atypical neoplastic, often pleomorphic cells that invade other tissues. "ARTN and NRTN genes are expressed most abundantly in osteoblastic OS cells, GDNF in carcinoma associated fibroblasts, and PSPN in endothelial cells." (PMID 40686838, 2025). "Our findings demonstrated that the NRTN gene exhibited no significant DE between plasmocytes and carcinoma associated fibroblasts (P-value = 1)." (PMID 40686838, 2025). "The NRTN gene was not DE between osteoclasts and carcinoma associated fibroblasts (P-value = 1.43 × 10−2)." (PMID 40686838, 2025). "It was observed that the NRTN gene exhibited no significant DE between carcinoma associated fibroblasts and endothelial cells (P-value = 1)." (PMID 40686838, 2025). "Moreover, NRTN mRNA expression is upregulated in some cancers, such as kidney renal papillary cell carcinoma (KIPR) and ovarian cancer (OV) from TCGA." (PMID 37566075, 2023). "NRTN, which is produced by the salivary gland epithelium during development, participates in the maintenance of neuronal-epithelial interactions in cases of damage, such as therapeutic irradiation (IR) in cancer." (PMID 32252363, 2020). "Furthermore, the NRTN gene was not DE between myeloid cells 1 and carcinoma-associated fibroblasts (P-value = 1)." (PMID 40686838, 2025). "Furthermore, the NRTN gene was not DE between osteoblastic OS cells and carcinoma-associated fibroblasts (P-value = 1)." (PMID 40686838, 2025). "This idea is supported by the upregulation of neuronal receptors such as AMAPR, NMDAR, GFRα1, GFRα2, GFRα3, AChR, L1-CAM, and NCAM and their ligands, including glutamine, GDNF, NRTN, ARTN, and Ach, in cancers." (PMID 37566075, 2023). "Cancer cells can communicate with the peripheral nervous system, through the release of molecules that are also made by neurons, including the GFLs, ARTN, GDNF, and NRTN." (PMID 32252363, 2020). "Although chemokines and neurotrophic factors with chemoattractive properties such as NGF, GDNF, artemin, or neurturin have long been studied in the context of NI in PDAC, the cytoskeletal adaptations of cancer cells during their nerve-directed migration have not been in the focus." (PMID 37607005, 2023).
neurodegenerative disease (2 papers, 2014 to 2020). A disorder of the central nervous system characterized by gradual and progressive loss of neural tissue and neurologic function. "Some of them like GDNF and neurturin (NRTN) have been tested in clinical trials for PD and other neurodegenerative diseases." (PMID 25136294, 2014).
neurologic diseases (2 papers, 2007 to 2025). "A growing body of literature suggests neurturin may represent a promising therapeutic agent for both central and peripheral neurologic diseases states, enhancing survival, differentiation, and regeneration of neurons alone or synergistically with other molecules." (PMID 17341313, 2007).
NRTN also shares sentences with these, for which no sentence is quoted: acute myeloid leukemia (1 paper); adenocarcinoma (1); amyotrophic lateral sclerosis (1); bladder cancer (1); bone cancer (1); brain tumors (1); breast carcinoma (1); Canavan disease (1); Cirrhosis (1); diabetes (1); immune disorders (1); inflammatory skin disease (1); neuroblastoma (1); Obesity (1); osteoarthritis (1); osteomyelitis (1); prostate carcinoma (1); psychiatric disorder (1); Stroke (1); Urinary incontinence (1); vitamin B complex deficiencies (1).